HDGFL3 (HDGF like 3)
Description:
Enhances DNA synthesis and may play a role in cell proliferation.
Synonyms: HRP-3; HDGF-2; HDGF2; HDGFRP3; CGI-142
Tractability: Small molecule: a structure with a bound ligand is known. PROTAC: ubiquitination databases record sites on it.
Gene: Protein-coding gene on chromosome 15 (83,112,738 to 83,208,424, reverse strand). Ensembl gene ENSG00000166503.
Subcellular location: Nucleus
Subcellular location (Human Protein Atlas): Nucleoplasm
Gene Ontology:
Molecular function: microtubule binding; tubulin binding
Biological process: microtubule polymerization; negative regulation of microtubule depolymerization; neuron projection development
Cellular component: extracellular region; nucleoplasm; nucleus; cytosol; cytoplasm
Genetic constraint (gnomAD): Loss-of-function variants: 1 observed, 17.92 expected, observed/expected ratio (o/e) 0.0558, 90% interval 0.019 to 0.26. The upper end of that interval is the gene's LOEUF score, 0.26, which puts it in group 1 of 6, group 1 being the genes least tolerant of losing a copy. Missense variants: 171 observed, 175.4 expected, observed/expected ratio (o/e) 0.97, 90% interval 0.86 to 1.11. Synonymous variants: 77 observed, 67.03 expected, observed/expected ratio (o/e) 1.15, 90% interval 0.95 to 1.39.
Homologues: Orthologues: chimpanzee HDGFL3 (100% identical), macaque HDGFL3 (99% identical), guinea pig HDGFL3 (99% identical), rat Hdgfl3 (98% identical), mouse Hdgfl3 (97% identical), rabbit HDGFL3 (91% identical), pig HDGFL3 (90% identical), tropical clawed frog hdgfl3 (86% identical). Paralogues in human: HDGFL2 (56% identical), HDGF (48% identical), PSIP1 (46% identical), HDGFL1 (37% identical).
Diseases named in the same sentence as HDGFL3 in open-access papers:
HDGFL3 is named in the same sentence as 14 diseases in open-access papers, as found by Europe PMC text mining. Sharing a sentence is not in itself a finding about the gene and the disease. The quoted sentences say what the papers report.
hepatocellular carcinoma (7 papers, 2006 to 2023). A malignant tumor that arises from hepatocytes. "HDGF-related protein 3 (HRP3, also known as HDGFL3) belongs to the family of HDGF-related proteins (HRPs) and plays an essential role in hepatocellular carcinoma pathogenesis." (PMID 31162607, 2019).
HDGFL3 also shares sentences with these, for which no sentence is quoted: malaria (26 papers); parasitemia (7); infection (5); falciparum malaria (4); breast carcinoma (3); cancer (2); amyotrophic lateral sclerosis (1); co-infection (1); colorectal carcinoma (1); Hypertension (1); liver cancer (1); ovarian carcinoma (1); squamous cell carcinoma (1).